CAT (catalase)
Diseases named in the same sentence as CAT in open-access papers (continued):
Sharing a sentence is not in itself a finding about the gene and the disease.
Obesity (continued). "Previous studies have reported associations of SNPs SOD2 rs4880, GPX7 rs835337, GPX1 rs1050450, CAT rs1001179 with obesity, body mass index and body fat in Brazilian, Mexican, British, Finnish, Chinese, Caucasian, and African–American adult populations." (PMID 40867795, 2025). "In the present study, we investigated the direct and modulatory effects of four antioxidant enzyme SNPs (SOD2 rs4880, GPX1 rs1050450, GPX7 rs835337, and CAT rs1001179) on the relationships among obesity-related oxidative stress markers in Mexican children." (PMID 40867795, 2025). "In obesity, it has been proposed that the overexpression of catalase suppresses oxidative stress obesogenic pathways." (PMID 39836643, 2025). "We aimed to assess the direct and modulatory effects of SNPs in antioxidant genes (SOD2 rs4880, GPX1 rs1050450, GPX7 rs835337, CAT rs1001179) on the relationships among obesity-related oxidative stress markers in Mexican children." (PMID 40867795, 2025). "Obesity typically results in a decreased antioxidant enzymes level, such as glutathione peroxidase (GPx), catalase (CAT), and superoxide dismutase (SOD), which lessens an individual's antioxidant defenses in contrast to those who are of a normal weight." (PMID 39803213, 2025). "A total of 1675 children with normal weight and 1271 children with obesity were included to assess the association of four SNPs, SOD2 rs4880, GPX7 rs835337, GPX1 rs1050450, and CAT rs1001179, with obesity." (PMID 40867795, 2025). "Reduction in antioxidant enzyme activities such as glutathione, SOD, and catalase has been observed in adipose tissue isolated mitochondria from individuals with obesity and DM." (PMID 40710581, 2025). "Consequently, low CAT activity among obese and diabetic groups compared to healthy groups supports the notion that oxidative stress and defects in antioxidant enzyme function may be a predisposing factor in obesity that leads to the development of T2DM." (PMID 39014510, 2024). "In our study, children with obesity showed significantly higher CAT and GPx enzyme activity than children with normal weight." (PMID 38671905, 2024). "Persistent symptoms of obesity progressively diminish antioxidant capacities, resulting in decreased activity of antioxidant enzymes like CAT, SOD, and GPx, ultimately leading to complications associated with obesity." (PMID 39519447, 2024). "At the same time, the low levels of CAT observed in obesity are partially due to increased S-nitrosation of the enzyme." (PMID 39176098, 2024). "In umbilical cord plasma, triglyceride, protein carbonyl, and catalase activity were significantly elevated in the maternal obesity group compared with the lean controls (p = 0.0482, 0.0291, and 0.0347, respectively)." (PMID 39409195, 2024). "In the case of CAT, a previous study conducted with Asian children reported that the gene expression of CAT, which is mainly related to CAT enzyme activity, was higher among children with obesity than those with normal weight." (PMID 38671905, 2024). "The increased production of ROSs in obesity is accompanied by a lower activity of the enzymes responsible for ROSs removal (GPx, CAT, SOD)." (PMID 39061938, 2024). "To evaluate the initial stages of the damage caused by obesity, we studied the pro-inflammatory cytokine IL-6, MDA, and endogenous antioxidants GSH and catalase-specific activity in the brain." (PMID 38182767, 2024). "In most cell and animal experiments, the activity or expression of CAT was measured after H2O2 treatment or steatosis induced by obesity." (PMID 37759451, 2023). "Regarding perirenal adipose tissue as happened for GRed, obesity induced day/night differences in the expression of Catalase with higher levels at night, as would be expected in the active phase of the rat." (PMID 36674472, 2023).
Obesity (continued). "In a previous study, a physiological increase in cardiac catalase activity levels in mitochondria due to obesity was able to limit H2O2 levels while maintaining normal insulin responsiveness in cardiac tissue." (PMID 37238003, 2023). "Several important antioxidants, including GSH, SOD, GPx, CAT, and GR, have a significant correlation with the suppression of cancer development, obesity, and inflammatory diseases." (PMID 37107216, 2023). "Increased serum FFA levels accompanying obesity have been reported to cause an increase in NOX mRNA expression and a decrease in the expression of genes encoding antioxidant enzymes (NQO1, SOD and catalase) in endothelial cells." (PMID 35073378, 2022). "Based on these results, 1) WTD-induced obesity downregulates the catalase mRNA; and 2) the combination of repeated GSs and diet-induced obesity synergistically upregulates the NOX2 and p47phox mRNAs and downregulates the SOD2 mRNA." (PMID 35073378, 2022). "Induction of antioxidants, especially Mn-SOD and CAT, can reduce oxidative stress and prevent the complications of obesity in children." (PMID 35978387, 2022). "Then, we compared malonodialdehyde (MDA), superoxide dismutase (SOD), catalase (CAT), and glutathione peroxidase (GPx), including overweight and obesity, hyperandrogenemia, and IR in the PCOS group." (PMID 35207512, 2022). "Then, MDA, SOD, CAT, and GPx were compared, differentiating between overweight and obesity, hyperandrogenemia, and IR in the PCOS group." (PMID 35207512, 2022). "LF-CQPC07 upregulated the mRNA expression of SOD1, GSH-Px, SOD2, CAT, and GSH1 to increase the body’s antioxidant capacity and inhibit oxidative stress, thereby relieving liver damage and inflammation caused by obesity." (PMID 33531053, 2021). "In this study, while 20 WBC treatments did not influence plasma oxidative and antioxidative status in people with extreme obesity, CAT activity was observed to significantly increase in this group." (PMID 33560197, 2021). "In the experimental model of HFD-induced obesity, we noticed significantly decreased CAT values after two-week CBD administration in the rats fed the high-fat diet (−12.8%, p < 0.05, vs. the HFD group) only in the red gastrocnemius muscle." (PMID 34064937, 2021). "The L. sakei ob4.1 strain, isolated from the feces of a subject with obesity, showed high catalase activity, which was regulated by oxidative stress at the gene transcription level." (PMID 34190593, 2021). "mRNA expression of NADPH oxidase (Nox)-2 and catalase were unaffected by exposure to maternal obesity or hydralazine." (PMID 33735324, 2021). "In obesity, adipose tissue exhibited the lower activities of antioxidant enzymes (CAT, SOD, and GSH-Px) and the higher levels of cytokines (TNF-α, IL-1β, and IL-6) and ROS generation." (PMID 32104715, 2020). "Cardiac oxidative stress and high CAT activity levels are correlated with boosted fat metabolism, high-fat diet and obesity." (PMID 32098399, 2020). "Genetic studies showed that catalase is involved in metabolic syndromes, including obesity, type 2 diabetes, atherosclerosis, hyperglycemia, dyslipidemia, and hypertension." (PMID 32561832, 2020). "Antioxidant enzymes such as CAT, SOD, and GPx have an important role in reducing the oxidative stress and inhibition of inflammation associated with obesity." (PMID 31366053, 2019). "The observed higher CAT activity points to the compensatory mechanism in simple obesity against augmented ROS production." (PMID 31737129, 2019). "Antioxidant sources can be depleted and the activity of enzymes such as superoxide dismutase (SOD) and catalase can decrease when obesity persists for a long time (CAT)." (PMID 29843440, 2018). "Several SNPs of CAT, GPX, and SOD have been associated with obesity and its principal comorbidities." (PMID 29339975, 2018). "Genetic polymorphisms of antioxidant enzymes CAT, GPX, and SOD are involved in the etiology of obesity and its principal comorbidities." (PMID 29339975, 2018).
Obesity (continued). "Consistent with the body of literature linking obesity with oxidative stress, glutathione peroxidase and catalase enzyme activity and mRNA expression were shown to be lower in adipose tissue of obese animals." (PMID 28545081, 2017). "Serum and liver MDA levels increased by 158.8% and 81.7% (P < 0.001) and serum TAC, liver SOD, CAT, and GSHPx decreased by 67.6, 54.7, 34.4%, and 56.4% upon obesity induction." (PMID 28396714, 2017). "Further research is needed to better understand the metabolic effects of catalase in adipose tissue in the presence of obesity in vivo." (PMID 27023799, 2016). "Excessive H2O2 levels are degraded by catalase (CAT), the activity of which is decreased in obesity." (PMID 27023799, 2016). "Our findings suggest an important role of catalase in the protection of adipocytes against the oxidative stress and metabolic complications observed in obesity through the regulation of H2O2 levels, which exerts complex signaling functions." (PMID 27023799, 2016). "Aiming to replicate the conditions observed in obesity, where CAT is inhibited, we intended to elucidate the degree to which catalase activity is responsible for the alterations found in obese adipose tissue using the inhibitor 3-AT in human adipocytes." (PMID 27023799, 2016). "We previously found that CAT+ mice were resistant to obesity induced reductions in NO bioavailability." (PMID 26186712, 2015). "Furthermore, a reduction in the activity of antioxidant enzymes such as superoxide dismutase (SOD), catalase (CAT), and glutathione peroxidase (GPx) has been observed in obesity." (PMID 40944223, 2025). "The antioxidant activity of CAT is significantly diminished in adults with obesity." (PMID 38703299, 2024). "Accordingly, upregulation of CAT may promote insulin sensibility and protect against obesity by influencing energy expenditure processes." (PMID 38703299, 2024). "Considering the relationship between NAFLD, obesity, IR and T2DM, it is suggested that CAT and its gene polymorphisms may play an important role in the coexistence of these pathologies." (PMID 37759451, 2023). "Catalase inhibition increased pro-inflammatory macrophage accumulation but decreased alternatively activated macrophage accumulation in eWAT, indicating that endogenous catalase may be a critical regulator of obesity-related inflammation and IR." (PMID 37153549, 2023). "In addition, the coexistence with IR of obesity and/or lipid profile disorders activates mechanisms associated with MDA activation and catalase." (PMID 35207512, 2022). "Green tea powder intervention could improve the oxidative stress state of the HFD-induced obesity mice, which elevated the antioxidant enzyme activities in the liver and colon, including CAT, SOD, and GSH levels." (PMID 36245513, 2022). "This study shows that A. officinarum possesses antihypertensive and diuretic effects possibly mediated through attenuation of obesity markers (weight gain, leptin, and adiponectin), lipid parameters and appreciable diuretic, catalase, and superoxide dismutase activities." (PMID 34305591, 2021). "This preliminary study aimed to explore the association of 12 SNPs related to superoxide dismutase (SOD), catalase (CAT), glutathione peroxidase (GPX), glutathione-S-transferase (GST), and nitric oxide synthase (NOS) genes with obesity susceptibility in a Saudi population." (PMID 33924357, 2021). "Similarly, it has been reported that obesity can increase CAT activity in female mice, also consistent with our findings." (PMID 33282873, 2020). "Therefore, we used catalase-knockout (CKO) mice to elucidate the involvement of excessive H2O2 in the development of obesity." (PMID 33080438, 2020). "The aim of this study was to evaluate the levels of paraoxonase 1 (PON1), lectin-like oxidized LDL receptor-1 (LOX-1), antioxidant enzymes (superoxide dismutase (SOD), catalase (CAT), and glutathione peroxidase (GPx)), and lipid peroxidation processes in the course of obesity." (PMID 31737129, 2019).
Obesity (continued). "Moreover, embelin was reported to reduce body weight gain, blood pressure, and serum lipid levels and increase superoxide dismutase, catalase, and glutathione levels in high-fat diet-induced obesity in rats." (PMID 31635287, 2019). "The importance of obesity-related factors and oxidative stress in nephropathy risk is also supported by our finding that variants in the FTO and CAT genes, which encode the fat mass and obesity-associated and catalase proteins, respectively, are associated with this diabetic complication." (PMID 29410390, 2018). "It is thus conceivable that catalase activity may increase in response to the increased H2O2 that accompanies adipose tissue expansion in obesity, as observed in visceral fat in the present study." (PMID 28545081, 2017). "Incubation with SOD and catalase restores PVAT vasorelaxant function in animal obesity." (PMID 26910225, 2015). "Reductions in SOD and CAT have been associated with obesity and metabolic dysfunction, which may suggest that, compared with female rats, FR50-treated male rats are more prone to develop metabolic derangement and obesity." (PMID 41154756, 2025). "Therefore, the present study aims to investigate both the direct and modulatory effects of four SNPs in antioxidant genes (SOD2 rs4880, GPX1 rs1050450, GPX7 rs835337, CAT rs1001179) on the relationships among obesity-related oxidative stress markers in Mexican children." (PMID 40867795, 2025). "Unlike the adult population, the study “Obesity Is Associated with Oxidative Stress Markers and Antioxidant Enzyme Activity in Mexican Children” reported increased enzymatic activity of catalase and glutathione peroxidase in obese children compared to their normal-weight peers." (PMID 40724604, 2025). "Surprisingly, laminitis reported in this study was not linked to obesity but associated with insulin levels <20 mU/L, lower body weight, and glucose levels, along with higher concentrations of albumin, catalase, glucose, insulin, and IGF-1 compared to obese mares." (PMID 40901060, 2025). "Moreover, except for NOX4 expression, which trended lower, NFE2L2, NQO1, SOD2, and CAT gene expression declined in patients with obesity (BMI = 47–74) with NASH and fibrosis (NAS = 5–6; fibrosis score = 1–2) to levels evident in patients with obesity with nonsteatotic livers." (PMID 38060313, 2023). "GSNO has been shown to promote the S-nitrosation of catalase, which modulates its activity in processes like growth, development and response to stress in plants and animals, and GSNO-directed inhibition of catalase by S-nitrosation has been linked to obesity in humans." (PMID 34434934, 2021). "Moreover, erythrocyte catalase activity was lower in children with insulin resistance and obesity." (PMID 28545081, 2017). "Despite the heterogeneity of the models and tissues investigated, collective evidence suggests that obesity-induced oxidative stress may not result from catalase deficiency, and is often, though not consistently, associated with catalase up-regulation." (PMID 28545081, 2017). "Moreover, CAT erythrocyte activity was lower in children with insulin resistance and obesity." (PMID 24562334, 2014). "In the present study, the non significant change in the CAT enzyme activity in liver and heart tissues of obese rat may be due to increases oxygen consumption of previous tissues due to obesity and the change of CAT enzyme activity is dependent on oxygen consumption." (PMID 21812977, 2011). "Research has indicated that the onset of obesity results in a reduction in the activity of key antioxidant enzymes, including SOD, CAT, and GSH‐PX, thus inducing oxidative stress." (PMID 40260060, 2025). "Previously, rats with overweight and obesity have been shown to exhibit increases in enzymatic activity, specifically superoxide dismutase (SOD), catalase (CAT), and glutathione peroxidase (GPX), in the testis and epididymis." (PMID 40566611, 2025).
Obesity (continued). "Persistent inflammation in obesity can suppress endogenous antioxidants, such as superoxide dismutase (SOD), catalase (CAT), and glutathione peroxidase (GPx), due to excessive levels of adipokines secreted by fat cells in the body, leading to oxidative stress." (PMID 40871683, 2025). "A similar trend was observed in this study, where obesity reduced the activities of oxidative stress enzymes SOD, CAT, and GSH‐PX, while increasing oxidative damage markers such as MDA and GSH, as well as inflammatory factors IL‐6 and TNF‐α." (PMID 40260060, 2025). "First, in animal models of diet-induced obesity, Withaferin A supplementation reduced hepatic fat, restored hepatic insulin sensitivity, and increased superoxide dismutase (SOD), catalase (CAT), glutathione peroxidase (GPx), and GSH content in the liver." (PMID 39064738, 2024). "Catalase and SOD2 expressions in the placental tissue were significantly lower in the maternal obesity group compared to the maternal lean control (p < 0.0001 and p = 0.0011, respectively)." (PMID 39409195, 2024). "Obesity increases the gene expression of HO1 and decreases the relative gene expression of the antioxidant enzymes SODMn, GPx and Catalase, which makes PRAT more sensitive and dynamic as a visceral fat depot than SAT, which behaves as a more static fat depot." (PMID 36674472, 2023). "Fustine is a flavonoid that has been reported to have hypoglycemic, antioxidant, anti-arthritic, anti-obesity, and anti-cancer effects; it can reduce the level of MDA and increases the levels of GSH, SOD, and CAT in diabetic rats." (PMID 36832842, 2023). "In obesity-metabolic disorders, when antioxidative defense enzymes are depleted [such as superoxide dismutase (SOD), catalase (CAT), glutathione peroxidase (GPx)], XOD is being converted into XO." (PMID 36987421, 2023). "In the WE group, the serum levels of TC, TG, and LDL-C, and the activities of AST and ALT decreased, while the activities of antioxidant enzymes CAT, SOD, and GSH-Px increased compared with the obesity model group." (PMID 37297416, 2023). "Persistent inflammatory conditions seen in obesity can suppress endogenous antioxidants such as superoxide dismutase (SOD), catalase (CAT), and glutathione peroxidase (GPx) in the body." (PMID 37237937, 2023). "This antioxidant effect is indicated by restored SOD, CAT, and GSH-Px activities and decreased MDA levels, which contributes to the reduction in obesity and hepatic steatosis in the liver." (PMID 37685254, 2023). "Correlation analysis showed that 11 key OTUs were positively or negatively correlated with parameters related to metabolic disorders in obesity, including weight body gain, TC, TG, LDL-C, HDL-C, CAT, SOD, GSH and MDA." (PMID 36553852, 2022). "Such chronic maladaptations were observed with obesity, resulting in reduced antioxidant capacity through decreased activity of antioxidative enzymes such as superoxide dismutase (SOD), catalase (CAT), and glutathione peroxidase (GPx)." (PMID 34829546, 2021). "Also, obesity has been reported to induce systemic oxidative stress, resulting in a collapse in the antioxidant defense system characterized by decreased activity of catalase, superoxide dismutase, reduced glutathione levels, and an increase in the MDA marker of lipid peroxidation." (PMID 34122598, 2021). "Significant differences (p < 0.001) have been spotted in GPx and Catalase levels between SD and HFD, indicating that induced obesity can compromise antioxidant enzyme levels in plasma." (PMID 32708089, 2020). "Our study showed that diet-induced obesity markedly impaired the antioxidant status in heart tissues of HDF-treated rats by increasing the levels of TBARS and reducing the SOD, CAT, and GPx activities, compared to controls." (PMID 32190675, 2020). "Both the diabetic animal model and the obesity animal model demonstrated that the C. asiatica extract increased the GSH, CAT, and SOD activities, thereby improving the enzyme antioxidant system." (PMID 33013406, 2020).